HINT2 (histidine triad nucleotide binding protein 2)
Description:
Exhibits adenosine 5'-monophosphoramidase activity, hydrolyzing purine nucleotide phosphoramidates with a single phosphate group such as adenosine 5'monophosphoramidate (AMP-NH2) to yield AMP and NH2. Hydrolyzes adenosine 5'-O-p-nitrophenylphosphoramidate (AMP-pNA). Hydrolyzes fluorogenic purine nucleoside tryptamine phosphoramidates in vitro. May be involved in steroid biosynthesis. May play a role in apoptosis.
Synonyms: HIT-17
Tractability: Small molecule: a structure with a bound ligand is known. PROTAC: its protein half-life has been measured.
Target class: Enzyme; Hydrolase
Gene: Protein-coding gene on chromosome 9 (35,812,960 to 35,815,354, reverse strand). Ensembl gene ENSG00000137133.
Subcellular location: Mitochondrion
Subcellular location (Human Protein Atlas): Mitochondria
Pathways (Reactome):
Signal Transduction: RHOD GTPase cycle
Gene Ontology:
Molecular function: adenosine 5'-monophosphoramidase activity; protein binding; catalytic activity
Cellular component: mitochondrion; mitochondrial outer membrane; mitochondrial matrix
Genetic constraint (gnomAD): Loss-of-function variants: 17 observed, 19.61 expected, observed/expected ratio (o/e) 0.87, 90% interval 0.59 to 1.3. The upper end of that interval is the gene's LOEUF score, 1.3, which puts it in group 5 of 6, group 1 being the genes least tolerant of losing a copy. Missense variants: 217 observed, 208.27 expected, observed/expected ratio (o/e) 1.04, 90% interval 0.93 to 1.17. Synonymous variants: 96 observed, 83.25 expected, observed/expected ratio (o/e) 1.15, 90% interval 0.98 to 1.37.
Homologues: Orthologues: chimpanzee HINT2 (100% identical), macaque HINT2 (95% identical), dog HINT2 (90% identical), guinea pig HINT2 (90% identical), mouse Hint2 (86% identical), rat Hint2 (85% identical), tropical clawed frog hint2 (56% identical), zebrafish hint2 (55% identical), Drosophila melanogaster HINT1 (46% identical). Paralogues in human: HINT1 (46% identical), FHIT (16% identical).
Diseases named in the same sentence as HINT2 in open-access papers:
HINT2 is named in the same sentence as 36 diseases in open-access papers, as found by Europe PMC text mining. Sharing a sentence is not in itself a finding about the gene and the disease. The quoted sentences say what the papers report.
ocular melanoma (14 papers, 2019 to 2025). A melanoma that arises from the structures of the eye or ocular adnexa. "To determine if reduced HINT2 expression underlies the decreased proliferation observed upon enhancing m6A modification in ocular melanoma, we attempted to rescue this phenotype by inhibiting HINT2 expression in upregulated m6A cells (lanes 3, 4)." (PMID 31722709, 2019). "For example, ALKBH5-mediated m6A demethylation inhibits the translation of histidine triad nucleotide-binding protein 2 (HINT2), which promotes the malignant proliferation and metastasis of ocular melanoma cells." (PMID 38118002, 2024). "Regulates the translation of the tumor suppressor gene HINT2 to regulate ocular melanoma tumorigenesis." (PMID 36830067, 2023). "Histidine triad nucleotide binding protein 2 (HINT2), proved to be a tumor suppressor gene in ocular melanoma, was then determined to be the m6A-mediated target via MeRIP-Seq and RNA-seq assays." (PMID 36830067, 2023). "YTHDF1 promotes the translation of Histidine triad nucleotide binding protein 2 (HINT2)-methylated mRNA but reduces the m6A modification in ocular melanoma." (PMID 33692959, 2021). "YTHDF1 suppresses ocular melanoma through modulation of mRNA translation of histidine triad nucleotide-binding protein 2, a tumor suppressor in ocular melanoma." (PMID 32513173, 2020). "With the help of YTHDF1, the translation of methylated HINT2 mRNA, a tumour suppressor of ocular melanoma, was significantly accelerated, meaning m6A modification obviously inhibits the progression of ocular melanoma." (PMID 32303268, 2020). "Here, we discovered that m6A mRNA methylation regulates the translation of the tumor suppressor gene HINT2 and thereby regulates ocular melanoma tumorigenesis." (PMID 31722709, 2019). "HINT2 has been reported to act as a tumor suppressor in hepatocellular carcinoma and pancreatic cancer, and we confirmed its function in ocular melanoma." (PMID 31722709, 2019). "Mechanistically, YTHDF1 promoted the translation of methylated HINT2 mRNA, a tumor suppressor in ocular melanoma." (PMID 31722709, 2019). "Mechanistically, YTHDF1 promotes the translation of methylated mRNA of HINT2, a tumor suppressor in ocular melanoma." (PMID 31722709, 2019). "Moreover, YTHDF1 has been shown to augment the translation of methylated HINT2 mRNA, thereby suppressing the malignant progression of ocular melanoma." (PMID 40251202, 2025). "The ‘readers’, such as YTHDF1, could inhibit ocular melanoma by mediating m6A modification of HINT2 mRNA." (PMID 34446007, 2021). "In addition, YTHDF1 inhibits the growth and migration of ocular melanoma cells via facilitating the translation of histidine triad nucleotide binding protein 2 (HINT2)." (PMID 33928028, 2021). "To investigate whether these variations in protein expression occur in samples, we performed IF staining in ocular melanoma and normal tissue and found that HINT2 was indeed downregulated in tumor samples (p < 0.001)." (PMID 31722709, 2019). "Furthermore, polysome profiling analysis indicated a greater amount of HINT2 mRNA in the translation pool in ocular melanoma cells with higher m6A methylation." (PMID 31722709, 2019). "Notably, we found that knockdown of HINT2 only partially rescued the effect of knockdown of ALKBH5 on ocular melanoma cells, which indicates that there are other cofactors involved in tumorigenesis that are regulated by m6A modifications." (PMID 31722709, 2019). "Notably, lower HINT2 expression in ocular melanoma tissue samples was highly correlated with a poor prognosis (log rank test, p < 0.05)." (PMID 31722709, 2019). "We overexpressed HINT2 in ocular melanoma cells at both the mRNA and protein levels." (PMID 31722709, 2019). "Notably, cell proliferation, cell migration and colony formation were significantly inhibited and apoptosis was increased in ocular melanoma cells upon HINT2 overexpression." (PMID 31722709, 2019).
ocular melanoma (continued). "Here, we revealed for the first time that HINT2 is regulated by m6A modification, indicating that disturbances in RNA methylation homeostasis result in dysregulation of proliferation and mitochondrial apoptosis, which contributes to the progression of ocular melanoma." (PMID 31722709, 2019). "For instance, m6A methylation on histidine triad nucleotide-binding protein 2 (HINT2), a tumor suppressor, is recognized by YTHDF1 that promotes its translation and significantly inhibits the progression of ocular melanoma cells in ocular melanoma." (PMID 39087001, 2024). "m6A modification was decreased in ocular melanoma due to METTL3 downregulation and ALKBH5 upregulation, which promoted YTHDF1-mediated translation of histidine triad nucleotide-binding protein 2 (HINT-2), a tumor suppressor of ocular melanoma." (PMID 35164788, 2022). "Mechanistically, m6A methylation recognized by YTH N6-methyladenosine RNA binding protein 1 (YTHDF1) promotes translation of histidine triad nucleotide-binding protein 2 (HINT2), a tumor suppressor in ocular melanoma." (PMID 31722709, 2019). "Because HINT2 restrains cell growth and migration in ocular melanoma and shows reduced m6A methylation in tumors compared to normal cells, we hypothesized that decreased m6A modification might restrain tumor growth partially through upregulating HINT2 expression." (PMID 31722709, 2019).
melanoma (7 papers, 2019 to 2024). A malignant, usually aggressive tumor composed of atypical, neoplastic melanocytes. "The inhibitory factor HINT2 mRNA translation is stimulated by YTHDF1 in melanoma, and its absence enhances the anti-melanoma immune response." (PMID 38339157, 2024). "Initial study on melanoma demonstrated that YTHDF1 can promote translation by binding Histidine Triad Nucleotide Binding Protein 2 (HINT2) transcripts, that in turn promotes tumor cell proliferation, inhibits apoptosis and confers a poor prognosis." (PMID 33692959, 2021). "To determine the role of HINT2 in tumor characteristics in vivo, we performed subcutaneous transplantation of ocular melanoma cells with different treatments." (PMID 31722709, 2019). "However, in melanoma YTHDF1 may act as a tumor suppressor that can promote the translation of the tumor suppressor gene histidine triad nucleotide binding protein 2 to inhibit tumor development." (PMID 36581942, 2022). "However, in melanoma, YTHDF1 might function as a tumor suppressor by facilitating the translation of the tumor suppressor gene histidine triad nucleotide-binding protein 2, thereby inhibiting tumor evolution." (PMID 38255219, 2024).
colorectal cancer (3 papers, 2017 to 2023). A primary or metastatic malignant neoplasm that affects the colon or rectum. "HINT2 encodes a histidine triplet protein that plays a role in various cancers, and HINT2 down-regulation can promote colorectal cancer migration and metastasis." (PMID 37415732, 2023). "As a tumor suppressor gene, HINT2 is downregulated in pancreatic cancer and hepatocellular cancer, endometrial cancer and colorectal cancer, preventing the mitochondrial apoptosis pathway and leading to poor survival." (PMID 31722709, 2019). "Here, we showed that HINT2 expression is lower in primary colorectal cancer (CRC) and metastasis tissues than in normal colorectal tissues, and that HINT2 abundance is inversely correlated with CRC tumor stage." (PMID 28088787, 2017).
ischemia (3 papers, 2021 to 2025). A hypoperfusion of the BLOOD through an organ or tissue caused by a PATHOLOGIC CONSTRICTION or obstruction of its BLOOD VESSELS, or an absence of BLOOD CIRCULATION. "In mice, EC-specific overexpression of HINT2 protects coronary microvascular function and preserves angiogenic potential with ischemia-reperfusion injury." (PMID 41026534, 2025). "Previous studies have shown that HINT2 protects heart from ischemia injury." (PMID 39968501, 2025).
cardiac hypertrophy (2 papers, 2024 to 2025). "Reports indicate THRB's regulation of genes linked to myocardial hypertrophy, including Myh6, Adrb1 and Atp2a2,28, 29 highlighting its role in myocardial remodelling and explaining the downregulation of HINT2 expression." (PMID 38546629, 2024). "While baseline heart phenotypes were unaffected by HINT2 deletion, it significantly exacerbated AB‐induced cardiac hypertrophy, evidenced by increased normalized HW/BW and HW/TL." (PMID 38546629, 2024). "Contrary to previous results, HINT2 knockdown resulted in increased hypertrophic markers with Ang II treatment, indicating worsened myocardial hypertrophy." (PMID 38546629, 2024). "Taken together, these findings indicate that HINT2 absence exacerbates cardiac injury induced by increased cardiac pressure, amplifying both cardiac hypertrophy and fibrosis, aggravated AB‐induced cardiomyocyte apoptosis." (PMID 38546629, 2024). "HINT2 may protect against pressure overload‐induced myocardial hypertrophy by regulating the mitochondrial complex I pathway." (PMID 38546629, 2024). "H&E staining showed more severe AB‐induced pathological cardiac hypertrophy in HINT2‐KO mice compared to WT mice, characterized by enlarged cardiomyocyte CSA and increased levels of hypertrophic markers in HINT2‐KO mice." (PMID 38546629, 2024).
cardiac ischemia (2 papers, 2021 to 2024). "Histidine triad nucleotide-binding 2 (HINT2) has been reported to modulate [Ca2+]m via the MCU complex, and our previous work demonstrated that HINT2 improved cardiomyocyte survival and preserved heart function in mice with cardiac ischemia." (PMID 34914018, 2021).
hepatocellular carcinoma (2 papers, 2017 to 2019). A malignant tumor that arises from hepatocytes. "Histidine triad nucleotide-binding 2 (HINT2), a member of the histidine triad proteins family, sensitizes cells to apoptosis in hepatocellular carcinoma." (PMID 28088787, 2017). "HINT2 is localized exclusively in the mitochondrial matrix and is a tumor suppressor in human hepatocellular carcinoma." (PMID 28088787, 2017). "HINT2 expression is generally downregulated in human hepatocellular carcinoma cells and HINT2 appears to sensitize these cells to apoptosis." (PMID 28088787, 2017).
myocardial infarction (2 papers, 2021 to 2024). Gross necrosis of the myocardium, as a result of interruption of the blood supply to the area, as in coronary thrombosis. "Overexpression of HINT2 in mice improves post‐myocardial infarction (MI) heart function and preserves MMP and respiration in hypoxic cardiomyocytes." (PMID 38546629, 2024). "Importantly, blocking the MCU complex with Ru360 limited the myocardial infarction size, whereas activating the MCU complex nullified the protective effects of HINT2 on infarction expansion." (PMID 34914018, 2021).
uveal melanoma (2 papers, 2016 to 2023). A melanoma derived from melanocytes of the uveal tract. "Moreover, post-transcriptional enhancement of HINT2 expression by m6A alteration has been shown to indicate advanced uveal melanoma with a poor prognosis." (PMID 37124608, 2023).
acute pancreatitis (1 paper, 2025). An acute inflammatory process that leads to necrosis of the pancreatic parenchyma. "A study in acute pancreatitis found that the drug Emodin targeted HINT2 to promote mitochondrial oxidative phosphorylation (OXPHOS), attenuating inflammatory responses and cell necrosis." (PMID 40307568, 2025).
adenovirus infection (1 paper, 2024). "We confirmed our findings through in vitro experimentation using isolated NRCMs, modulating HINT2 expression via adenovirus infection." (PMID 38546629, 2024).
endothelial dysfunction (1 paper, 2021). In vascular diseases, endothelial dysfunction is a systemic pathological state of the endothelium (the inner lining of blood vessels) and can be broadly defined as an imbalance between vasodilating and vasoconstricting substances produced by (or acting on) the endothelium. "However, increased nitrite has been reported to improve endothelial dysfunction and attenuate infarct size in myocardial IR injury, still supporting a protective role of HINT2 in cardiac microcirculation." (PMID 34914018, 2021).
head and neck squamous cell carcinoma (1 paper, 2018). A squamous cell carcinoma that arises from any of the following anatomic sites: lip and oral cavity, nasal cavity, paranasal sinuses, pharynx, larynx, and salivary glands. "HINT2, the enhancer of zeste homolog 2 (EZH2) is overexpressed or activated in many human cancers including head and neck squamous cell carcinoma (HNSCC)." (PMID 30011966, 2018).
heart failure (1 paper, 2025). Inability of the heart to pump blood at an adequate rate to meet tissue metabolic requirements. "Therapeutic strategies enhancing HINT2 expression or supplementing NMN may reduce cardiac damage and heart failure caused by DOX." (PMID 39968501, 2025).
Hepatic steatosis (1 paper, 2025). Steatosis is a term used to denote lipid accumulation within hepatocytes. "Taken together, these findings suggest that HINT2 attenuates hepatic steatosis, inflammation, fibrosis and mitochondrial damage in MASH mice and plays an important protective role in different stages of MASLD." (PMID 40307568, 2025). "Knockout of Hint2 exacerbated diet-induced hepatic steatosis, inflammation, fibrosis and mitochondrial damage in mice, whereas overexpression of Hint2 attenuated these effects." (PMID 40307568, 2025). "Hint2 knockout exacerbates diet-induced hepatic steatosis, inflammation, fibrosis and mitochondrial damage in mice." (PMID 40307568, 2025).
infarction (1 paper, 2021). A localised pathological necrosis of tissue resulting from obstruction of the blood supply usually by a thrombus, an embolus, or vascular torsion. "Ultimately, endothelial-specific overexpression of HINT2 reduced the infarction size, indicating that HINT2-mediated microvascular improvement inhibited myocardial necrosis in the acute reperfusion phase." (PMID 34914018, 2021).
ischemic heart disease (1 paper, 2024). "In the heart, several studies have reported the significant role of HINT2 in ischemic heart disease." (PMID 38546629, 2024). "Currently, it is known that HINT2 plays a significant role in ischemic heart diseases." (PMID 38546629, 2024). "Prior studies have demonstrated that HINT2 plays a crucial role in ischemic heart disease, but its importance in cardiac remodelling remains unknown." (PMID 38546629, 2024).
leukemia (1 paper, 2022). A malignant (clonal) hematologic disorder, involving hematopoietic stem cells and characterized by the presence of primitive or atypical myeloid or lymphoid cells in the bone marrow and the blood. "To validate the function of SETD1A target genes (COX15, HMBS, UROS, RRNAD1, NUDT18, GSTZ1, HINT2, and COX18) in leukemia cells, we performed a CRISPR-based competitive cell proliferation assay in doxycycline-inducible Cas9-expressing MOLM-13 leukemia cells." (PMID 36450243, 2022).
lymph node metastasis (1 paper, 2017). "Multivariate analysis showed that HINT2 mRNA levels was downregulated in CRCs without lymph node metastasis than that in lymph node positive ones(P < 0.01)." (PMID 28088787, 2017).
metabolic dysfunction-associated steatohepatitis (1 paper, 2025). Metabolic dysfunction-associated steatohepatitis (MASH, formerly known as nonalcoholic steatohepatitis or NASH) is a type of fatty liver disease. "To explore the regulatory effects of HINT2 in the next stages of MASLD, we induced a metabolic dysfunction-associated steatohepatitis (MASH) mouse model using WD + SW." (PMID 40307568, 2025).
tumor (16 papers, 2017 to 2025). "In contrast, YTHDF1 has an anti-tumor effect on ocular melanoma by promoting the translation of m 6A-modified mRNA of HINT2 which is a tumor suppressor." (PMID 40483535, 2025). "In contrast, YTHDF1 acts as a tumour suppressor in melanoma where it promotes the translation of the tumour suppressor HINT2, thus inhibiting tumour development." (PMID 33461542, 2021). "On the other hand, in ocular melanoma, YTHDF1 promotes the translation of m6A-containing HINT2 mRNA, a tumor suppressor." (PMID 31921664, 2019). "HINT2 is a member of the superfamily of histidine triad AMP-lysine hydrolase proteins, which are closely associated with mitochondrial metabolism and tumor suppression." (PMID 31722709, 2019). "A semi-quantitative analysis revealed that HINT2 expression is progressively lost with increasing tumor stage." (PMID 28088787, 2017). "HINT2 downregulation increased tumor migration and invasion in vitro, promoted CRC cell metastasis in vivo, and increased expression of epithelial-to-mesenchymal transition (EMT) markers." (PMID 28088787, 2017). "Two upregulated proteins, APC and HINT2, also emphasize a tumor-suppressive role." (PMID 37834160, 2023). "However, in ocular melanoma, YTHDF1, as a tumor suppressor, promotes the translation of HINT2 mRNA (a tumor suppressor) containing m6A." (PMID 37437245, 2023). "Although in normal melanoma, the other family member YTHDF1 does not reduce cell proliferation and migration, it can promote translation of the histidine triad nucleotide-binding protein 2 tumor suppressor in ocular melanoma, being shown to promote tumor regression in vitro and in vivo." (PMID 34105069, 2021). "In addition, GSEA showed that HINT2 promoted apoptosis and cell death in tumor cells." (PMID 31722709, 2019). "We confirmed that HINT2 expression was lower in CRC tissues than in normal colon mucosa, especially during metastasis, and that HINT2 abundance was inversely correlated with CRC tumor stage." (PMID 28088787, 2017). "Importantly, the cell proliferation rates of ALKBH5 knockdown cells after HINT2 knockdown were only partially comparable to those of the control cells with normal ALKBH5 expression (lanes 1, 4, 6G-H), suggesting that there are more tumor-related genes regulated by their m6A modifications." (PMID 31722709, 2019).